ACSM6 (acyl-CoA synthetase medium chain family member 6)
Description:
Catalyzes the activation of fatty acids by CoA to produce an acyl-CoA, the first step in fatty acid metabolism.
Synonyms: C10orf129; bA310E22.3
Tractability: PROTAC: ubiquitination databases record sites on it.
Gene: Protein-coding gene on chromosome 10 (95,194,200 to 95,228,929, forward strand). Ensembl gene ENSG00000173124.
Subcellular location: Mitochondrion
Pathways (Reactome):
Metabolism: Beta oxidation of butanoyl-CoA to acetyl-CoA
Gene Ontology:
Molecular function: fatty acid ligase activity; fatty-acyl-CoA synthase activity; medium-chain fatty acid-CoA ligase activity; acid-thiol ligase activity
Biological process: acyl-CoA metabolic process; fatty acid biosynthetic process
Cellular component: mitochondrion; mitochondrial matrix
Genetic constraint (gnomAD): Loss-of-function variants: 31 observed, 45.88 expected, observed/expected ratio (o/e) 0.68, 90% interval 0.51 to 0.91. The upper end of that interval is the gene's LOEUF score, 0.91, which puts it in group 3 of 6, group 1 being the genes least tolerant of losing a copy. Missense variants: 467 observed, 560.39 expected, observed/expected ratio (o/e) 0.83, 90% interval 0.77 to 0.9. Synonymous variants: 161 observed, 200.12 expected, observed/expected ratio (o/e) 0.8, 90% interval 0.71 to 0.92.
Homologues: Orthologues: chimpanzee ACSM6 (98% identical), tropical clawed frog acss2.2 (22% identical), zebrafish acss2l (20% identical), Caenorhabditis elegans acs-2 (15% identical), Caenorhabditis elegans acs-1 (15% identical). Paralogues in human: ACSM4 (46% identical), ACSM3 (45% identical), ACSM5 (43% identical), ACSM1 (42% identical), ACSM2B (41% identical), ACSM2A (41% identical), ACSS2 (21% identical), ACSS3 (21% identical), ACSS1 (21% identical), ACSF2 (20% identical), AACS (17% identical), ACSF3 (16% identical), and 1 more.
Diseases named in the same sentence as ACSM6 in open-access papers:
ACSM6 is named in the same sentence as 5 diseases in open-access papers, as found by Europe PMC text mining. Sharing a sentence is not in itself a finding about the gene and the disease. The quoted sentences say what the papers report.
bladder cancer (2 papers, 2023 to 2024). "Through single-cell sequencing, we determined that ACSM6, an oncogene that is highly expressed in bladder cancer, promotes the abilities of proliferation, cloning, migration, and invasion." (PMID 39334304, 2024). "In summary, ACSM6 is expected to become a novel biomarker for predict bladder cancer progression." (PMID 39334304, 2024). "In this study, we investigate the latent effect of ACSM6 on bladder cancer (BLCA)." (PMID 37426827, 2023).
thymoma (1 paper, 2023). A neoplasm arising from the epithelial cells of the thymus. "This study found that ACSM6 may act as a potential molecular biomarker for assessing the tumor microenvironment status in various types of cancer, particularly in BLCA and thymoma, and may lead to the formation of a non-inflammatory TME in BLCA." (PMID 37426827, 2023).
tumor (2 papers, 2023 to 2024). "We conducted a comprehensive investigation to examine the association between ACSM6 and the tumor microenvironment (TME) in BLCA." (PMID 37426827, 2023). "Vast major steps in the tumor immune cycle in the high ACSM6 group were downregulated, including cancer cell antigen release, immune cell activation and recruitment, and cancer cell killing." (PMID 37426827, 2023). "In summary, ACSM6 is a potential biomarker for predicting tumor microenvironment status in BLCA." (PMID 37426827, 2023). "We investigated the potential immunological effects of ACSM6 in regulating the BLCA tumor microenvironment by analyzing its correlation with immunomodulators, anti-cancer immune cycles, immune checkpoints, tumor-infiltrating immune cells, and the T-cell inflamed score (TIS)." (PMID 37426827, 2023). "Notably, the high ACSM6 group better turned to be effected by immunosuppressive tumor therapy." (PMID 37426827, 2023). "The key point is that ACSM6 can also lead to a non-inflammatory immune microenvironment by inhibiting the chemotaxis and tumor killing ability of CD8+ T cells." (PMID 39334304, 2024). "Our study showed that the presence of ACSM6 plays the promotion to the development of a non-inflammatory TME in BLCA, which in turn results in resistance to tumor immunotherapy." (PMID 37426827, 2023).
cancer (1 paper, 2023). A tumor composed of atypical neoplastic, often pleomorphic cells that invade other tissues. "ACSM6 was negatively associated with multiple key steps in the anticancer immune cycle, particularly the release of cancer cell antigens and the recruitment of immune cells." (PMID 37426827, 2023). "The immunological role of ACSM6 was determined and the cancer types most affected by ACSM6 were screened using pan-cancer analysis." (PMID 37426827, 2023). "However, the connection between the ACSM family and cancer has rarely been reported, especially for ACSM6." (PMID 37426827, 2023). "In the Xiangya cohort, we observed a negative correlation between ACSM6 expression and several critical steps in the cancer immune cycle, which was consistent with our findings, suggesting that when ACSM6 is highly expressed, TIL infiltration in TME is downregulated." (PMID 37426827, 2023).
ACSM6 also shares sentences with these, for which no sentence is quoted: vitiligo (1 paper).